MIR624 (microRNA 624)
Synonyms: hsa-mir-624; MIRN624; mir-624
Gene: MicroRNA gene on chromosome 14 (31,014,646 to 31,014,742, reverse strand). Ensembl gene ENSG00000207952.
Gene Ontology:
Biological process: miRNA-mediated post-transcriptional gene silencing
Cellular component: RISC complex
Homologues: Orthologues: chimpanzee ptr-mir-624 (100% identical), macaque mml-mir-624 (97% identical).
Diseases named in the same sentence as MIR624 in open-access papers:
MIR624 is named in the same sentence as 2 diseases in open-access papers, as found by Europe PMC text mining. Sharing a sentence is not in itself a finding about the gene and the disease.
MIR624 shares sentences with these, for which no sentence is quoted: psychiatric disorder (1 paper); schizophrenia (1).